RNU6-162P (RNA, U6 small nuclear 162, pseudogene)
Gene: Small nuclear RNA gene on chromosome 7 (143,574,746 to 143,574,848, forward strand). Ensembl gene ENSG00000252037.
Homologues: Orthologues: chimpanzee U6 (98% identical), macaque U6 (93% identical), macaque U6 (92% identical), macaque U6 (91% identical), dog U6 (71% identical), rabbit U6 (71% identical), pig U6 (67% identical), mouse Gm25619 (65% identical), mouse Gm26072 (65% identical), mouse Gm26271 (65% identical), guinea pig U6 (63% identical), rat U6 (60% identical), and 2 more. Paralogues in human: RNU6-267P (99% identical), RNU6-144P (78% identical), RNU6-16P (78% identical), RNU6-46P (78% identical), RNU6-480P (78% identical), RNU6-1316P (77% identical), RNU6-196P (77% identical), RNU6-310P (77% identical), RNU6-434P (77% identical), RNU6-1 (76% identical), RNU6-102P (76% identical), RNU6-10P (76% identical), and 1288 more.